GCKR (glucokinase regulator)
Diseases named in the same sentence as GCKR in open-access papers (continued):
Sharing a sentence is not in itself a finding about the gene and the disease.
Obesity (37 papers, 2010 to 2025). Accumulation of substantial excess body fat. "Elevated IL-6 and CRP levels are common in obesity, and although direct evidence linking GCKR variants to obesity is limited, this pathway warrants further investigation." (PMID 41150798, 2025). "The effect allele of GCKR cis‐pQTLs was always associated with higher glucose, insulin resistance, obesity, and other traits; meanwhile, it reduced serum uric acid, alcohol consumption, and blood lipids, which implies a side effect of GCKR intervention." (PMID 39921581, 2025). "This study indicated that the GCKR gene is also a novel therapeutic target in the treatment of obesity and obesity-associated metabolic disorders." (PMID 37829557, 2023). "Binary logistic regression has shown a significant association of the GCKR rs1260326 variant with obesity in NAFLD as compared to normal-weight subjects." (PMID 37829557, 2023). "Meta-analysis and GWAS analysis indicate that the GCKR rs1260326 has possibly impaired the hepatic lipid metabolism and significantly contributes to the development of obesity and obesity-associated metabolic disorder including NAFLD and T2DM." (PMID 37829557, 2023). "The genetic variant GCKR rs1260326 was significantly linked with NAFLD and T2DM, while the GCKR rs1260326 was significantly associated with the progression of obesity only in NAFLD subjects." (PMID 37829557, 2023). "In man circulating ANGPTL8 levels correlate with obesity and interestingly also with the human GCKR rs1260326 variant." (PMID 37031802, 2023). "The common GCKR variant has a more pronounced effect on hepatic fat accumulation and plasma triacylglycerols in individuals with obesity and hyperglycaemia." (PMID 36035124, 2022). "We found multiple positive associations of GCKR rs780094-T with GLs and GLPs, and these lipids were also associated with insulin resistance, obesity and elevation of ALT concentrations." (PMID 31308433, 2019). "A recent study found that the variants of GCKR were associated with obesity in postmenopausal women." (PMID 30110382, 2018). "Similarly, genetic variations in the GCKR expression can also regulate glucose metabolism and insulin sensitivity in obesity-associated metabolic disorders including NAFLD and T2DM." (PMID 37829557, 2023). "Thus, this study was conducted to evaluate the genetic association and contribution of GCKR rs1260326 to induce obesity in NAFLD and T2DM subjects in a local population of South Punjab." (PMID 37829557, 2023). "Heterozygous loss-of-function mutations in NR0B2 in OMIM (*604630) are associated with mild early-onset obesity, whereas truncating mutations in GCKR may be linked to increased levels of blood triglycerides." (PMID 35207755, 2022). "This analysis suggests that genetic variation at the GCKR locus may modulate NAFLD risk associated with obesity and/or elevated triglyceride levels." (PMID 34841290, 2021). "A recent study showed an association between GCKR mutations and high FPG levels, triglyceride measurement, and obesity." (PMID 38162681, 2023). "In a cohort study, glucokinase regulatory protein, a gene related to the regulation of glucokinase, was associated with triglyceride elevation and NAFLD among youths with obesity in a cohort study." (PMID 37941769, 2023). "Similar to previous studies, this study also indicated that the GCKR rs1260326 possibly contributed to the pathology of T2DM and insulin resistance through lipogenesis or obesity-associated pathways." (PMID 37829557, 2023). "Glucose metabolic abnormality related to GCK/GCKR expression leads to obesity, an important contributor of hyperuricemia development." (PMID 35365700, 2022). "These SNPs were in/near the following genes: LEP, SLC32A1 (solute carrier family 32 member 1), GCKR (glucokinase regulatory protein), CCNL1 (cyclin-L1), and FTO (fat mass and obesity-associated)." (PMID 31766143, 2019).
Obesity (continued). "Having demonstrated that the enhancer regulates GCKR transcription, we investigated GCKR haplotype-specific expression in human liver biopsies from subjects that participated in the Kuopio Obesity Surgery (KOBS) study." (PMID 28683826, 2017). "Thus, the GCKR rs1260326 was a genetic risk factor and significantly linked to NAFLD and T2DM in the local population, which can contribute to the development of obesity and insulin resistance." (PMID 37829557, 2023). "The GCKR rs1260326 mutant allele (CC) was considerably higher in subjects with obesity and insulin resistance independent of the high fat and glucose uptake." (PMID 37829557, 2023). "Nevertheless, some of these SNPs (rs1260326 (GCKR), rs13233571 (BCL7B), rs2847281 (PTPN2), and rs4129267 (IL6R) predicting hsCRP and rs630014 (ABO), rs651007 (ABO), and rs687289 (ABO) predicting IL-6) were associated with obesity-related traits." (PMID 28819125, 2017). "While these results are preliminary, significant heterogeneity of GCK localization between individuals is consistent with previous reports of variation in human GCK localization and activity due to factors including genetic variation in GCKR and metabolic conditions such as obesity or T2D." (PMID 24586696, 2014). "In addition, variation in GCKR, encoding glucokinase regulatory protein, and FTO, the fat mass and obesity associated gene, were associated with serum triglyceride and BMI respectively." (PMID 20161779, 2010). "Furthermore, a previous study also reported a significant association of the GCKR rs1260326 with high fasting glycemia in the young Mexican population, without a significant association with obesity." (PMID 37829557, 2023). "In conclusion, the GCKR rs1260326 is a highly prevalent SNP in NAFLD and T2DM subjects, which possibly contributed to obesity, insulin resistance, and metabolic disorders in our population." (PMID 37829557, 2023). "Moreover, stratified analysis by ethnicity, liver disease, source of control, NAFLD assessment, age, and obesity has demonstrated all subgroups were significantly correlated with increased risk of NAFLD, suggesting GCKR rs780094 may have a high effect on NAFLD incidence." (PMID 30646922, 2019). "Several of the observed DMCs were located in genes related to T2D or obesity, such as ALOX12, PAMR1, and GNAS in WB; IRS1, LEP, and ADIPOQ in SAT; LCAT, FOXA2, KCNQ1, and GCKR in VAT; and PKD4, HNF4A, XBP1, and PON1 in LT." (PMID 29466957, 2018). "The interactions between obesity and TM6SF2 E167K and GCKR have also been described." (PMID 36035124, 2022). "GCKR, ABCB11, CDKAL1, CDKN2B, NT5C2, and APOC1 were associated with metabolically unhealthy in individuals with normal weight but not in those with obesity." (PMID 33500527, 2021). "Thus, multiple previous studies have reported a significant genetic association between GCKR rs1260326 and NAFLD with and without obesity." (PMID 37829557, 2023). "GCKR, ABCB11, CDKAL1, CDKN2B, NT5C2, and APOC1 were associated with metabolically unhealthy phenotypes in individuals with normal weight but not in those with obesity." (PMID 33500527, 2021). "He found GCKR, ABCB11, CDKAL1, CDKN2B, NT5C2, and APOC1 gene were associated with metabolically unhealthy phenotypes in individuals with normal weight but not in those with obesity, showing that certain genetic polymorphisms may also have an impact on the metabolic health in NWO populations." (PMID 39777912, 2025).
gout (33 papers, 2012 to 2025). A condition characterized by painful swelling of the joints, which is caused by deposition of urate crystals. "Specifically, the gout-linked MAV is an eQTL targeting GCKR, a glucokinase inhibitor typical of gout." (PMID 37107615, 2023). "Most of these studies identified a strong correlation between the genetic variants of the GCKR polymorphisms, including rs126032610,27–29,42,43 and rs78009410,11,26,27,30,38–42, and hyperuricemia and/or gout development." (PMID 35365700, 2022). "Several previous studies explored the role of the GCKR variants in regulating the serum UA levels and/or gout." (PMID 35365700, 2022). "The SNP rs780094 (C > T) in GCKR is strongly associated with gout in the male Han-Chinese population." (PMID 34986901, 2022). "Apart from the T allele, the A allele of rs780094 in GCKR has been consistently shown to be associated with the risk of gout in Chinese and Japanese populations." (PMID 35365700, 2022). "Studies in American, Chinese and Japanese cohorts showed that rs780093, rs1260326, rs6547692 and rs780094 of GCKR gene were associated with gout in general, or male population." (PMID 30123371, 2018). "This is especially interesting given the recently reported interaction between GCKR rs780094 (in very strong linkage disequilibrium with rs1260326), alcohol, and gout risk." (PMID 29976226, 2018). "In mediation analysis of GCKR, a strong direct effect of the urate-associated SNP on gout risk was demonstrated (beta 0.351, standard error (SE) 0.051, P < 1.00 × 10−8)." (PMID 29976226, 2018). "Presumably, the urate-raising and gout risk allele of GCKR results in increased production of gout-causing metabolites through glycolysis." (PMID 28679452, 2017). "And 11 of the significant variants were from the gout associated loci (GCKR, SLC2A9, ABCG2, CNIH2, MYL2-CUX2 (ALDH2) and BCAS3)." (PMID 28642574, 2017). "Recently, we revealed for the first time that the following 3 loci were associated with gout at the genome-wide significance level: rs1260326 of GCKR, rs4073582 of CNIH-2 and rs2188380 of MYL2-CUX28." (PMID 27181629, 2016). "Of these loci, GCKR has an effect size that is consistently higher in gout; GCKR is associated with gout in European, Chinese, Japanese, and Polynesian sample sets (odds ratio (OR) = 1.3 to 1.5 in sample sets where gout is clinically ascertained)." (PMID 25889045, 2015). "The “A” allele of rs780094 in GCKR gene has been validated to be risk allele for gout consistently in Chinese, Japanese and New Zealand European and Polynesian case–control sample sets." (PMID 26290326, 2015). "This is consistent with the hypothesis that GCKR controls gout risk through its physiological role in glycolysis, presumably resulting in increased endogenous UA production." (PMID 35365700, 2022). "Furthermore, the GCKR polymorphism rs1260326 (C > T) was associated with increased gout risk (OR = 1.14, p = 8.2 × 10−6) and increased SU levels (Effect size = 0.074, p = 1.2 × 10−44) in individuals of European ancestry." (PMID 33810064, 2021). "ADH1B and GCKR were associated with gout, and ADH1B alone with hypertension." (PMID 31998841, 2020). "This systematic analysis provides the first evidence for an interaction of alcohol consumption (an established dietary risk factor for gout) with previously identified urate/gout-associated loci GCKR and A1CF that are predominantly involved in glycolysis and lipid homeostasis." (PMID 28679452, 2017). "Interestingly, GCKR interacts with alcohol to reduce the risk of gout." (PMID 35922835, 2022). "Noteworthy, the GCKR protein is associated with modulating some metabolic functions; hence, this finding might partially suggest a biological mechanism for developing cardiometabolic disorders, including HU and gout." (PMID 34986901, 2022).
gout (continued). "Among the other genes significantly associated with gout, seven loci have also been previously identified in GWAS, including those in the genes SLC17A1, GCKR, SLC22A11, ADH1B, MLXIPL, RREB1 and SLC16A9." (PMID 41075270, 2025). "GCKR was found to interact with allopurinol and febuxostat, both approved for the treatment of gout, highlighting its direct relevance to gout pathogenesis and therapy." (PMID 41075270, 2025). "ABCG2, GCKR, MLXIPL, and cytochrome P450 family 1 subfamily A member 2 (CYP1A2) are variants associated with coffee consumption habits, and GCKR and ABCG2 are associated with low coffee intake and a high gout risk." (PMID 35813212, 2022). "Genome-wide association studies (GWASs) have been successful in identifying genetic variants that are associated with hyperuricemia or gout, including SLC2A9, ABCG2, GCKR, and SLC22A11." (PMID 35484537, 2022). "Previous candidate analyses and GWASs11,12,58 of clinically defined gout identified nonsynonymous variants of gout susceptibility genes such as ABCG2 (rs72552713, Q126X; rs2231142, Q141K) and GCKR (rs1260326, L446P)." (PMID 30993211, 2019). "Despite the association of GCKR and ABCG2 with both gout and reduced coffee intake, our mediation analysis indicates that the dominant mechanism for GCKR and ABCG2 on gout risk is not through coffee consumption." (PMID 29976226, 2018). "For GCKR and ABCG2, association with gout was observed for both the presence of at least one urate-raising allele as well as by number of urate-raising alleles." (PMID 29976226, 2018). "As an example, a previous GWAS implicated the Glucokinase regulatory protein (GCKR), which encodes protein associated with hepatic mitochondria, as one gout susceptibility gene." (PMID 29976239, 2018). "Of these, 13 variants were common (MAF ≥ 5%) and located in known serum urate GWAS loci, including rs2231142 (Q141K) in ABCG2 (beta: 0.22, p = 2.4 × 10−32; OR for gout: 2.05, p = 1.7 × 10−15), and other variants in SLC2A9, ABCG2, GCKR, SLC17A1, and SLC17A414." (PMID 30315176, 2018). "The urate-increasing GCKR and ABCG2 alleles were associated with gout (multivariate adjusted p < 5 × 10−8 for both), but the urate-increasing MLXIPL and CYP1A2 alleles were not." (PMID 29976226, 2018). "In mediation analysis, the direct effects of GCKR and ABCG2 accounted for most of the total effect on gout risk, with much smaller indirect effects mediated by coffee consumption." (PMID 29976226, 2018). "Six of the genes (A1CF, GCKR, ABCG2, TRIM46, SLC17A1 and HNF4G (novel gout-associated gene)) were still significantly associated with gout in males after multiple correction (all PFDR < 0.05)." (PMID 28252667, 2017). "Interaction of any alcohol exposure with GCKR (rs780094) and A1CF (rs10821905) influenced the risk of gout in Europeans (interaction term 0.28, P = 1.5 × 10−4; interaction term 0.29, P = 1.4 × 10−4, respectively)." (PMID 28679452, 2017). "Rather, the loci (GCKR and A1CF) interacting with alcohol consumption in determining the risk of gout in Europeans are involved in glycolysis and apolipoprotein metabolism, respectively." (PMID 28679452, 2017). "Some of the previously reported gout associated loci (except ALDH16A1), including ABCG2, SLC2A9, GCKR, ALDH2 and CNIH2, were replicated." (PMID 28642574, 2017). "Three SNPs, rs780094 in GCKR, rs1183201 in SLC17A1 and rs505802 in SLC22A12 were confirmed to be significantly associated with gout and SUA concentrations." (PMID 26290326, 2015). "Three SNPs, rs780094 in GCKR, rs1183201 in 17A1 and rs505802 in SLC22A12 were significantly associated with gout in our samples." (PMID 26290326, 2015). "GCKR rs780093 (in strong LD with rs780094 in HapMap-CEU and HapMap-CHB, r2 = 1.0) was nominally associated with gout in Europeans and Chinese." (PMID 26290326, 2015). "For example, there are loci associated with control of serum urate levels that contain genes that are also associated with serum Tg levels (GCKR, MLXIPL, A1CF) and gout." (PMID 25432151, 2014).
gout (continued). "Recent GWAS identified genetic variants in urate transporters (ABCG2, SLC2A9, SLC22A11) and metabolic genes (GCKR, ADH1B) to be associated with the transition from hyperuricaemia to gout, and several of these associated with serum urate (SU) and gout in previous studies." (PMID 35633389, 2022). "Furthermore, GCKR gene mutations accelerate the transition from asymptomatic HUA to gout, and its SNP rs1260326 is associated with a higher risk of gout." (PMID 35922835, 2022). "The urate-associated SNPs for both GCKR and ABCG2 were significantly associated with gout." (PMID 29976226, 2018). "In these models, the association of both GCKR and ABCG2 with gout were also observed." (PMID 29976226, 2018). "Association of coffee consumption with gout was independent of all SNPs, and association of GCKR and ABCG2 SNPs with gout was independent of coffee consumption." (PMID 29976226, 2018). "In this study, HNF4G, SLC17A1 and GCKR played an important role in serum urate concentrations and gout risk in males but not in females, also suggesting the different contributions of genetic effects between different genders." (PMID 28252667, 2017). "Therefore, we performed a genetic association study of these SUA loci (PDZK1, GCKR, SLC2A9, LRRC16A, SLC17A1, SLC16A9, SLC22A11 and SLC22A12) in gout patients and normal control volunteers of Han Chinese origin." (PMID 26290326, 2015). "After removing rs780094 in the GCKR gene according to leave-one-out analysis, recalculating the main IVW estimate suggested a causal effect of fasting insulin on increased serum urate (β = 0.802, 95% CI: 0.514–1.090, P < 0.001) and risk of gout (OR = 3.293, 95% CI: 1.030–10.532, P = 0.045)." (PMID 35992130, 2022). "Furthermore, alcohol exposure eliminated the risk effect of glucokinase regulator (GCKR) on gout in people of European but not Polynesian origin." (PMID 35484537, 2022). "Interestingly, three genes (PDZK1, GCKR and HNF4G) associated with urate influenced the risk of gout, but the other five genes (TCF7L2, LRRC16A, ESR1, NRXN2 and ALPK1) did not, suggesting that elevated serum urate concentration is necessary but not sufficient for the pathogenesis of gout." (PMID 28252667, 2017). "We found significant association of uric acid concentrations with three gout-related SNPs (rs780094 in GCKR, corrected p = 3.94E−5; rs1183201 in SLC17A1, corrected p = 0.005; rs505802 in SLC22A12, corrected p = 0.003) and of triglycerides with rs780094 (located in GCKR, corrected p = 2.96E−4)." (PMID 26290326, 2015). "It is assumed that using GCKR as a therapeutic target for GDM reduces the plasma glucose level and also improves the glomerular filtration rate while, on the other hand, leading to hypertriglyceridemia and gout." (PMID 39921581, 2025). "In the absence of alcohol exposure, genetic variants in the GCKR and A1CF genes have a stronger role in determining the risk of gout." (PMID 28679452, 2017). "In the absence of alcohol exposure, genetic variants in the GCKR and A1CF genes have a stronger role in gout." (PMID 28679452, 2017). "Although the urate-raising GCKR and ABCG2 alleles were associated with both lower coffee consumption and higher risk of gout, mediation analysis demonstrated that these SNPs largely influence gout risk directly, rather than indirectly through their dual effect on coffee consumption." (PMID 29976226, 2018).